TIMP1 (TIMP metallopeptidase inhibitor 1)
Diseases named in the same sentence as TIMP1 in open-access papers (continued):
Sharing a sentence is not in itself a finding about the gene and the disease.
infection (continued). "IL-22 and TIMP1 expression was found to be similar at all time-points point infection." (PMID 37218575, 2023). "Some researchers suggest that TIMP-1 may inhibit pathogen clearance during infection by limiting MMP-driven lymphocyte penetration into the CNS." (PMID 30572657, 2018). "To validate that TIMP-1 down-regulation was causing an increase in miR-125a-5p levels, we infected the cells with different multiplicity of infection (MOI) of sh-TIMP-1 lentivirus or a non-targeted control." (PMID 29507665, 2018). "Interestingly, less distinct intestinal immunopathology was accompanied by lower colonic expression levels of the matrix-degrading enzyme MMP-2 and its endogenous inhibitor TIMP-1 seven days following ∆htrA as compared to the parental strain infection." (PMID 24883112, 2014). "Furthermore, our results showed that infection increased TIMP-1 expression by resident macrophages, and we also found increased metalloproteinase expression following infection (data not shown)." (PMID 24416445, 2014). "Moreover, colonic expression of MMP-2 and TIMP-1 was similar in Lcn2+/+ and Lcn2−/− mice after infection, excluding their involvement in this process." (PMID 24465207, 2014). "Thus, an imbalance between the circulating levels of specific MMPs and TIMPs—especially increased MMP-1 and MMP-8 to TIMP-4 and decreased MMP-1 and MMP-7 to TIMP-1 and 2—is characteristic of filarial lymphedema in the presence of active infection." (PMID 22679524, 2012). "Moreover, MMP-9 and TIMP-1 expressions were lower in the combined H. pylori-infection and NSAID-use group than in the H. pylori-infected group (P < 0.05)." (PMID 22645431, 2012). "Finally, the ratio between pro-MMP9/TIMP1 protein levels in the supernatant of S. aureus–stimulated samples was elevated in STAT3-deficient compared with WT BMDM, in particular at 48 h after infection." (PMID 37982695, 2024). "Considering the antagonistic functionality of MMP9 and TIMP-1, these data suggest that our control animals may still be actively remodeling lung tissue to combat infection, while the UA-treated animals with altered IL-17 signaling may be resolving the lung environment to repair functionality." (PMID 34869750, 2021). "However, TIMP-1, the inhibitor of metalloenzymes, increased with the time of infection." (PMID 33117360, 2020). "Furthermore, this altered MMP-9:TIMP-1 ratio is exacerbated in the presence of infection." (PMID 26691525, 2015). "However, since mycetoma is a localized infection, a localized reduction of TIMP-1 could result in higher MMP-9 levels in the lesion, which, in its turn, could be found in serum." (PMID 24675764, 2014). "Furthermore, TIMP-1 is expressed in invading T-cells and CNS-resident astrocytes during infection." (PMID 25436884, 2013). "Further research should include the correlation of MMP-9 with wound size, infection status, and healing trajectories in larger cohorts and aim to investigate MMP-9/TIMP-1 ratios as prognostic tools." (PMID 41189831, 2025). "To further explore the mechanisms behind PRV-induced blood-brain barrier permeability, we assessed the expression levels of MMP2, TIMP1, MMP9, and ZO-1 at various time points post-infection in bEnd.3 cells." (PMID 39436133, 2024). "Quantification of the expression of six inflammatory markers (IL-5, IL-8, IL-22, CCL20, TIMP1, CSF2) was carried out at 2, 24, and 48 hr post-infection." (PMID 37218575, 2023). "infection can change the levels of matrix metalloproteinases (MMP-2,-9) and the tissue inhibitor of MMPs (TIMP-1,-3) in the brain." (PMID 35563321, 2022). "We observed a strong connection of deep infection foci to higher MMP-8 and TIMP-1 levels throughout the 90 days observation period." (PMID 34043679, 2021). "As mentioned, we found that the expression of CXCL1, CXCL12, CCL2, CCL5 and TIMP-1 was significantly increased upon CGS-17 and CXZ-15 infection." (PMID 33081802, 2020).
infection (continued). "In early infection of EBV, BZLF1 expression increases in the days following infection, as does TIMP-1 in both its expression and secretion." (PMID 33228078, 2020). "Here, we assayed MMP2, MMP7, MMP9, TIMP1, and TIMP2, which have previously been described to be differentially expressed after infection of the CNS." (PMID 30442185, 2018). "In the present study, the inhibition of NLRP3 inflammasome by infection with AAV8-shNLRP3, successfully attenuated collagen deposition and increased expression of TIMP-1 in the liver that had been induced by S. japonicum infection." (PMID 28808303, 2017). "Infection increased secretion of cytokines/chemokines TNF-α, IL-6, TIMP-1, IL-1RA, G-CSF, TREM, KC, MIP-1α, MIP-1β, MCP-1, and MIP-2 in resident macrophages." (PMID 24416445, 2014). "The changes in the other four genes were more complex, but also depended on the time points: At day 3 post infection, Balb/c mice produced more MMP-13 and less MMP-8, MMP-9, and TIMP-1, but this trend was reversed at three later time points." (PMID 22665968, 2012). "In this study, the expression of both MMP2 and TIMP2 increased during LX-2 activation induced by TGF-β1; however, after AdNDRG2 infection, MMP2 was enhanced while TIMP2 levels decreased compared with AdLacZ controls (MMP9 and TIMP1 were undetectable)." (PMID 22110735, 2011). "Matrix metalloproteinase expression did not change with infection, potentially due to inhibition by TIMP-1." (PMID 41157615, 2025). "In vitro, heparinase treatment before infection led to a 52% increase in viral load (p = 0.0038) without altering MMP-7 or TIMP-1 protein levels." (PMID 39312544, 2024). "IL-33, IL-27, and TIMP-1 were lower than the limit of detection or showed no significant change from the mock infection model on both sides (data not shown)." (PMID 37725516, 2023). "Also, molecules such as TIMP-1, KC (CXCL1), and MIP-1 alpha (CCL3) showed inhibition upon E. japonica- infection in MyD88-independent manner." (PMID 38022511, 2023). "infection, there was a statistically significant difference in the MMP-9/TIMP-1 ratio." (PMID 35563321, 2022). "In the meanwhile, the host responds to this local infection and produces immune‐promoting cytokines, such as IL‐6, MIP‐2, granulocyte colony‐stimulating factor (G‐CSF) and tissue inhibitor of metalloproteinases 1 (TIMP‐1) to attract tumoral infiltration of various immune cells." (PMID 33854892, 2021). "Following infection by CV-B3, mice expressed IL-22 at higher levels, as well as collagen type I-A1, collagen type III-A1, and matrix metalloproteinase-9, while levels of tissue inhibitor of metalloproteinase-1 (TIMP-1) were decreased." (PMID 32704466, 2020). "Ultimately, the morphological examination showed no obvious pathological changes in the thalamus or lungs of control monkeys, whereas different pathological responses to EGFP-CA16 infection and EGFP-CA16 + MMP9 and EGFP-CA16 + TIMP-1 treatments were found in the thalamus and lungs." (PMID 30228270, 2018). "Infection leading to imbalance of MMP-8 and TIMP-1 may be related to initiation of preterm delivery." (PMID 28167848, 2017). "The present study investigated the regulation of TIMP-1 by DNA methylation with or without infection in the human placenta and fetal membranes." (PMID 26691525, 2015). "Infection increased secretion of cytokines/mediators IL-1RA, IL-6, TNF-α and TIMP-1." (PMID 24416445, 2014). "If MMP-9 levels increase during infection, those of TIMP-1 did not change, remaining at basal levels at all time points." (PMID 25436884, 2013). "Furthermore, colonic TIMP-1 mRNA expression was up-regulated 7 days following parental but not ∆htrA strain infection (p < 0.01)." (PMID 24883112, 2014). "In addition to early induction of cytokines, CA/07 infection induced two to three-fold greater concentrations of MCP-1, TIMP-1 and MIG at four days post-infection and two to four-fold greater concentrations of IP-10 at two and four days post-infection with NL/602." (PMID 24086762, 2013).
infection (continued). "In the acute phase, an increased expression of TIMP1, which is an endogenous inhibitor of the ECM-degrading matrix metalloproteinases, prevents collagen degradation and thus revealed matrix deposition in both wild-type and STAT3 KO mice 10 days after infection." (PMID 22675647, 2012). "Thus, filarial lymphedema with or without active infection is characterized by elevated levels of circulating TIMP-1 and TIMP-2 and decreased levels of TIMP-3." (PMID 22679524, 2012). "Infection of chorioamniotic membranes with E. coli induces an increase in the secretion of inactive forms and an association to ECM of active forms of MMP-2 and MMP-9 without changes in TIMP-1, -2, and -4." (PMID 21266053, 2011). "Linear regression analysis showed that TIMP-1 levels were associated with the 372 T/C genetic polymorphism of TIMP-1 (regression coefficient = 114.4; 95% CI = 31.71 to 197.14; P = 0.007), but not with site of infection (regression coefficient = 105.7; 95% CI = -45.12 to 256.48; P = 0.17)." (PMID 23706069, 2013). "Live T. gondii tachyzoites, but not multiplicity of infection (MOI)-equivalent amounts of tachyzoite lysate, selectively induced elevated Timp1, but not Timp2, expression." (PMID 40265926, 2025). "We observed increased expression of MMP-9, but not TIMP-1 or MMP-2, in both CHME-3 and ARPR-19 cells following infection with P. aeruginosa strains." (PMID 32423093, 2020). "Although there was no substantial difference in absolute MMP-3 and TIMP-1 levels in this patient group, a comparison of median values showed a marked decrease in MMP-3 in patients with prior infection history." (PMID 24412616, 2014). "Infection with L. major increased the secretion of TNF-α, IL-6, TIMP-1, IL-1RA, G-CSF and TREM, but not IL-1α or IL-1β." (PMID 24416445, 2014). "Higher collagen deposition after infection in Cyb5r3 SPC–KO mice was accompanied by significantly higher transcript levels of Mmp12, Mmp13, Mmp14, and tissue inhibitor of metalloproteinases 1 (Timp1) but neither Timp2 nor Timp3." (PMID 36749633, 2023). "TIMP-4 levels were lower during the acute phase of infection, persisting as such even when MMP-9 and TIMP-1 have already decreased, until eosinophil meningitis was not definitely recovered, suggesting that TIMP-4 plays a crucial role in the proteolytic balance of BBB damage, in these patients." (PMID 25436884, 2013).
cardiovascular disease (34 papers, 2011 to 2026). "MMP9 and Tissue inhibitors of metalloproteinases 1 (TIMP1) were known to be associated with the risk of cardiovascular disease and several cancers." (PMID 35246549, 2022). "We investigated associations between plasma MMP-1, −2, −3, −9, −10 and TIMP-1, and cardiovascular disease (CVD) or microvascular complications in type 1 diabetic patients." (PMID 25848912, 2015). "TIMP1 was among the most central nodes and was selected among the targets of regulatory rewiring as increased TIMP1 protein levels have been associated with cardiovascular disease and severity." (PMID 39215134, 2024). "Interestingly, in a large longitudinal study, TIMP‐1 was a strong predictor of all-cause 10-year mortality, with most studied patients dying of cardiovascular disease." (PMID 31932967, 2021). "Relations of TIMP-1 to cardiovascular disease risk may have a variety of explanations." (PMID 21283828, 2011). "Our study provides a theoretical foundation for the treatment of MF-based cardiovascular diseases, with TIMP1 as a potential therapeutic target for LC to promote cardiovascular health and prolong life expectancy in older individuals." (PMID 36816804, 2023). "TIMP-1 is a crucial regulator of extracellular matrix degradation, and circulating TIMPs have been shown to be altered in several cardiovascular diseases." (PMID 35284430, 2021). "MMP-8 and TIMP-1 levels, as well as the MMP-8/TIMP-1 ratio in serum reflect progression and severity of cardiovascular diseases." (PMID 23637817, 2013). "Osteopontin (OPN), plasminogen activator inhibitor-1 (PAI-1) and tissue inhibitor of matrix metalloproteinase-1 (TIMP-1) are among the pro-fibrotic mediators that have been attributed to tissue degeneration and progression of cardiovascular disease." (PMID 21789188, 2011). "Therefore, we further tested the correlation between the relative levels of TIMP1, MMP2 and vWF (as assessed by slot blot) and several clinical/biochemical variables, and most common cardiovascular disease risk factors: age, BMI, or total cholesterol." (PMID 36362368, 2022). "It has been shown that changes in the level of MMP-9, as well as TIMP-1, associated with nonspecific inflammation, and the balance between MMP-9 and TIMP-1 depend on the etiological cause and stage of the cardiovascular disease continuum." (PMID 33224989, 2020). "The fact that TIMP-1 is the inhibitor also of other MMPs than MMP-9 (notably MMP-1), and these MMPs may also be important in the pathophysiology of cardiovascular disease, may partly explain why TIMP-1 was a stronger marker than MMP-9 of cardiovascular disease risk in this and other studies." (PMID 21283828, 2011). "TIMP-1 displays the highest affinity for MMP-9, which plays a significant role in immune cell function and fibrosis in cardiovascular disease." (PMID 41463322, 2025). "Within the extracellular matrix, the TIMP1 and TIMP2 are endogenous specific inhibitors of MMP-2 and MMP-9 against cardiovascular diseases." (PMID 35604403, 2022). "These protective effects are accompanied by decreased expression of the pro-fibrotic biomarkers OPN, TIMP-1 and PAI-1, which have been shown to correlate with the severity of cardiovascular diseases and end-organ damage in clinical studies." (PMID 21789188, 2011). "The dynamics and direction of changes at various stages of the cardiovascular disease continuum in the serum fibrosis markers, MMP-9 and TIMP-1 systems, may reflect an increase in fibrotic and decrease in antifibrotic processes already at the preclinical stage of HF." (PMID 33224989, 2020).
adenocarcinoma (19 papers, 2013 to 2025). A common cancer characterized by the presence of malignant glandular cells. "In addition, TIMP1 was found downregulated in adenocarcinoma compared to BPH and loss of TIMP1 correlated with biochemical recurrence in patients with localized PCa." (PMID 28471417, 2017). "TCGA analysis of the identified CAC-related core genes revealed a significant association between high expression of TIMP1 and ADAM8 with low overall survival of patients with both colon (COAD) and rectal (READ) adenocarcinomas." (PMID 36901742, 2023). "According to GSE29060 data, in HT-29 adenocarcinoma cells after a demethylation treatment 4 transcripts showed a minimally decreased expression (TIMP1, FADS1, CYP27B and SULT1A1), while PTGS2 was found to be upregulated." (PMID 26482433, 2015). "Single nucleotide polymorphisms (SNPs) at four TIMP (TIMP1-4) and three MMP genes (MMP2, MMP7 and MMP9) were genotyped in DNA samples from a prospective cohort of patients with primary adenocarcinoma of the GEJ admitted to the British Columbia Cancer Agency." (PMID 23527119, 2013). "We first assessed survival probability in the PanCancer Atlas from the TCGA consortium and found that higher TIMP1 mRNA expression is correlated with unfavorable prognosis both in Squamous‐cell and Adenocarcinoma (logrank p value = 0.0068 and 0.02, respectively)." (PMID 37759102, 2023). "After 24 h on a 3D RPM, the migration-related genes MMP-2, MMP-9, TIMP-1, and TIMP-2 were all upregulated both in a squamous (H1703) and in an adenocarcinoma (A549) cell line." (PMID 37048115, 2023). "When adenocarcinoma A549 cells were exposed to the microgravity environment, MMP-2, MMP-9, TIMP-1, and TIMP-2 showed higher expression in the MG than in the CONT at 24 h." (PMID 31601869, 2019). "Three human adenocarcinoma cell lines, PANC-1 (pancreatic), MCF-7 (breast), and T13 (TIMP-1–overexpressing MCF-7 clone) were cultured under basal conditions and stained for immunofluorescence analysis." (PMID 28030805, 2017).
kidney disease (14 papers, 2014 to 2024). "TIMP-1 levels are low in healthy kidneys, but have been shown to increase significantly in models of kidney diseases and are also associated with the extent of fibrosis." (PMID 36835210, 2023). "Although elevated levels of TIMP-1 and IL-6 have been associated with the development of kidney disease, data in this study indicate that kidney function is not affected despite a significant increase in these markers." (PMID 35204763, 2022). "In conclusion, we demonstrate for the first time an association between MMP-10 and TIMP-1 and the different stages of renal disease, as well as glomerular overexpression of Mmp10 in T2DM, which is prevented by blocking RAS." (PMID 31913319, 2020). "The activity of MMP-9 is controlled by TIMP-1, and both members of the MMP-9–TIMP-1 tandem are implicated in several disease states including cardiovascular and renal disease." (PMID 28791014, 2017). "TIMP-1 expression is universally upregulated in experimental kidney disease along with increased interstitial fibrosis." (PMID 39229378, 2024). "Some experimental studies found higher expression of TIMPs, particularly TIMP-1, in the renal tissue in the course of various kidney diseases." (PMID 32670438, 2020). "Regarding TIMP-1, although there is evidence supporting increased plasma and urinary concentrations in patients with renal disease, the data are inadequate." (PMID 30973283, 2019). "The results of the ELISA in the present study showed that MMP-2 and -9 and TIMP-1 and -2 were present in the sera from all kidney disease patients analyzed." (PMID 24520285, 2014). "The abundance of TIMP-1 in the kidneys has been shown to significantly increase in the majority of experimental models and several human renal diseases, showing positive correlation with the extent of fibrosis." (PMID 24396399, 2014). "For example, MMP-9 and MMP-2 have been elevated in various kidney disease models and humans, and urinary TIMP-1 has already been proposed as a marker of kidney function in patients after kidney transplantation and also its expressions have been increased in patients with CKD." (PMID 35205098, 2022). "Increased mRNA and protein levels of TIMP-1 were reported in several human and rodent models of different renal diseases, suggesting that TIMP-1 might be involved in the early events during the progression of renal diseases." (PMID 24678881, 2014). "Our study demonstrates that circulating MMP-10 is increased in T2DM, together with its inhibitor TIMP-1, starting at the earliest stages of DKD, and their concentration increases with the severity of kidney disease." (PMID 31913319, 2020). "Studies of various kidney disease models and patients with CKD have demonstrated a reduction in the activity and expression of MMP-9, in contrast with an increase in TIMP-1 expression." (PMID 24396399, 2014). "Interestingly, the findings of the present study are relevant for identifying an up-regulation of MMP-10 and TIMP-1 in T2DM, even before overt kidney disease is noted, and opens the door for future studies aiming at elucidating the mechanistic role of this MMP and its inhibitor on DKD." (PMID 31913319, 2020).